CPXM2 (carboxypeptidase X, M14 family member 2)
Description:
May be involved in cell-cell interactions.
Synonyms: CPX2; UNQ676
Tractability: Antibody: UniProt places it where antibodies can reach, with high confidence; UniProt predicts a signal peptide or a membrane-spanning region; its Gene Ontology location is reachable by antibodies, with medium confidence.
Gene: Protein-coding gene on chromosome 10 (123,706,207 to 123,940,267, reverse strand). Ensembl gene ENSG00000121898.
Subcellular location: Secreted
Gene Ontology:
Molecular function: metallocarboxypeptidase activity; zinc ion binding
Biological process: proteolysis
Cellular component: extracellular region
Genetic constraint (gnomAD): Loss-of-function variants: 56 observed, 71.83 expected, observed/expected ratio (o/e) 0.78, 90% interval 0.63 to 0.97. The upper end of that interval is the gene's LOEUF score, 0.97, which puts it in group 4 of 6, group 1 being the genes least tolerant of losing a copy. Missense variants: 816 observed, 882.22 expected, observed/expected ratio (o/e) 0.92, 90% interval 0.87 to 0.98. Synonymous variants: 352 observed, 352.53 expected, observed/expected ratio (o/e) 1, 90% interval 0.91 to 1.09.
Homologues: Orthologues: chimpanzee CPXM2 (99% identical), macaque CPXM2 (98% identical), pig CPXM2 (92% identical), guinea pig CPXM2 (91% identical), rabbit CPXM2 (90% identical), mouse Cpxm2 (89% identical), rat Cpxm2 (89% identical), dog CPXM2 (85% identical), tropical clawed frog cpxm2 (72% identical). Paralogues in human: AEBP1 (53% identical), CPXM1 (49% identical), CPD (29% identical), CPZ (27% identical), CPE (26% identical), CPN1 (25% identical), CPM (19% identical).
Diseases named in the same sentence as CPXM2 in open-access papers:
CPXM2 is named in the same sentence as 36 diseases in open-access papers, as found by Europe PMC text mining. Sharing a sentence is not in itself a finding about the gene and the disease. The quoted sentences say what the papers report.
cardiac hypertrophy (5 papers, 2022 to 2024). "The role of CPXM2 is still obscure, but recent publications have associated it with cardiac hypertrophy and failure." (PMID 38742935, 2024). "Our expression analysis of CPXM2 in endomyocardial biopsies of patients confirmed not only the expression of CPXM2 in the human heart but also significant CPXM2 upregulation in patients with various forms of cardiac hypertrophy." (PMID 34916661, 2022). "Differential increased cardiac expression of Cpxm2 was assigned to cardiac hypertrophy in SHRSP rats." (PMID 34916661, 2022). "Analysis of endomyocardial biopsies from patients with cardiac hypertrophy indicated significant upregulation of CPXM2 expression." (PMID 34916661, 2022). "We performed explorative analysis of CPXM2 mRNA expression in samples isolated from endomyocardial biopsies of human patients with cardiac hypertrophy and controls." (PMID 34916661, 2022). "Deeper knowledge about the pathophysiological role of CPXM2 in the development of cardiac hypertrophy and fibrosis could help us to implement novel targeted therapies for these conditions." (PMID 35216380, 2022). "Together, these studies indicate a potential role of miR-29b and miR-497 in fibrosis, cellular remodelling, and in the development of heart hypertrophy, which may be potentially mediated via modulating CPXM2 expression." (PMID 35216380, 2022). "Considering its co-localisation with Pdlim3, CPXM2 could potentially be involved in Pdlim3-mediated effects during the development of heart hypertrophy and fibrosis." (PMID 35216380, 2022). "These novel findings may help to shed more light on the—so far—widely unexplored expression control of CPXM2 and may help to further characterize the functional role of this factor in the context of arterial hypertension-induced heart hypertrophy and cardiac fibrosis." (PMID 35216380, 2022). "LV transcriptome analysis showed a molecular cardiac hypertrophy/remodeling signature in WT but not KO mice with significant upregulation of 1234 transcripts, including Cpxm2, in response to DOCA." (PMID 34916661, 2022). "Cpxm2 represents such a novel target, as it is upregulated in genetically hypertensive rat models, in response to DOCA-salt hypertension in mice, and in human patients with cardiac hypertrophy." (PMID 34916661, 2022). "CPXM2 mRNA expression was significantly higher in patients with cardiac hypertrophy (n = 20) than in patients without cardiac hypertrophy (n = 16, p = 0.0054)." (PMID 34916661, 2022).
gastric cancer (4 papers, 2022 to 2026). A primary or metastatic malignant neoplasm involving the stomach. "Recent studies on human osteosarcoma and gastric cancer reported CPXM2 overexpression as associated with an unfavorable prognosis." (PMID 38539556, 2024). "Knockdown of CPXM2 in cultured osteosarcoma and gastric cancer cells hindered cell proliferation and migration." (PMID 38539556, 2024). "CPXM2 and CHPF have not been reported in CRC, but have been found to promote gastric cancer progression." (PMID 38654221, 2024).
osteosarcoma (4 papers, 2019 to 2024). A usually aggressive malignant bone-forming mesenchymal neoplasm, predominantly affecting adolescents and young adults. "To date, a limited number of studies have surveyed the practical association between osteosarcoma carcinogenesis and CPXM2." (PMID 31651348, 2019). "We found that CPXM2 was overexpressed in osteosarcoma and that the overexpression was associated with an unfavorable prognosis and tumor node metastasis staging." (PMID 31651348, 2019). "Furthermore, our data observed that the CPXM2 expression is mainly expressed (15/27, 71.4%) in the osteoblastic osteosarcoma (P = 0.002), and notably associated with histologic grade (P = 0.011)." (PMID 31651348, 2019). "Furthermore, in the present study, we focused on the association between CPXM2 and 22 cases of pulmonary metastasis at the vascular level, our data revealed thatCPXM2 expression was significantly associated with distant metastasis in osteosarcoma patients." (PMID 31651348, 2019). "A eukaryotic expression plasmid was transfected into fetal osteoblast cells to overexpress CPXM2 and the endogenous CPXM2 in osteosarcoma cells was silenced through an RNA interference (RNAi) method transfection." (PMID 31651348, 2019). "Our data represent that, CPXM2, as an osteosarcoma proto-oncogene, was found to accelerate tumor progression by promoting osteosarcoma cell migration via modulation of EMT process, indicating that a detailed study of this putative marker is warranted." (PMID 31651348, 2019). "Our data represent that, CPXM2, an osteosarcoma proto-oncogene, significantly promoted the invasiveness of hFOB.1.19 cells." (PMID 31651348, 2019). "In the current study, we found that CPXM2 was overexpressed in osteosarcoma compared to normal bone tissues." (PMID 31651348, 2019). "Taken together, these results imply an active role for CPXM2 in promoting tumor aggressiveness via epithelial to mesenchymal transition (EMT) modulation in osteosarcoma." (PMID 31651348, 2019). "It was determined that the CPXM2 were low expressed in hFOB.1.19 cells at both mRNA and protein levels, but high expressed in osteosarcoma cell lines Saos2, 143B, MG63, and U2OS." (PMID 31651348, 2019). "The expression of CPXM2 in osteosarcoma cell lines (Saos2, 143B, MG63, and U2OS) and a human fetal osteoblast cell line (hFOB.1.19) were examined via RT-qPCR and western blotting." (PMID 31651348, 2019). "Currently, we found that CPXM2 expression was overexpressed in osteosarcoma sections, and that the upregulation of CPXM2 promoted metastatic phenotype of fetal osteoblast cells." (PMID 31651348, 2019). "The knockdown of CPXM2 in cultured osteosarcoma cells significantly impeded cell proliferation and migration." (PMID 31651348, 2019). "The expression of CPXM2 in osteosarcoma cell lines and tissues were explored by immunohistochemistry and western blotting assays." (PMID 31651348, 2019). "Taken together, these evidences indicated that that CPXM2 plays an active role in promoting osteosarcoma tumor aggressiveness via EMT modulation." (PMID 31651348, 2019). "Second, further studies are needed to confirm whether CPXM2 can be used as a serum prognostic biomarker for osteosarcoma patients." (PMID 31651348, 2019). "As EMT is a critical process that mediates tumor progression and metastasis, we postulate that CPXM2 may catalyze key molecules that regulate EMT in osteosarcoma." (PMID 31651348, 2019). "The expression levels of CPXM2 in a fetal osteoblast cell line with CPXM2 overexpressing and an osteosarcoma CPXM2-knockout cell line was confirmed via reverse transcription-quantitative polymerase chain reaction (RT-qPCR), western blotting and immunofluorescence." (PMID 31651348, 2019). "Moreover, an osteosarcoma cell line (U2OS) with a CPXM2-knockout was also settled up and it is illustrated that CPXM2-silencing lead to a suppression on metastasis in U2OS cells via modifying EMT process." (PMID 31651348, 2019).
osteosarcoma (continued). "Currently, the clinical relevance and function of CPXM2 in human osteosarcoma were investigated." (PMID 31651348, 2019). "However, CPXM2 expression was meaningfully associated with Enneking clinical stages (P = 0.003), TNM stage (P = 0.002), pulmonary metastasis at vascular level (P = 0.003) and, E-Cadherin expression (P = 0.004) in osteosarcoma patients." (PMID 31651348, 2019). "Currently, the specific impact of CPXM2 in osteosarcoma remains unclear." (PMID 31651348, 2019). "Western blotting analysis was also performed with the patient tissues in order to analyze the variations between noncancerous tissues and osteosarcoma tissues in CPXM2 expression." (PMID 31651348, 2019). "CPXM2 was notably upregulated in the 36 osteosarcoma tissues vs. the 36 noncancerous bone tissues (P = 0.0005)." (PMID 31651348, 2019). "However, at present there are no reports documenting the impact of CPXM2 in osteosarcoma tumorigenesis." (PMID 31651348, 2019). "Additionally, the CPXM2 expression was investigated in 36 osteosarcoma tissue samples and 36 noncancerous tissue samples." (PMID 31651348, 2019).
Alzheimer disease (3 papers, 2018 to 2023). A progressive, neurodegenerative disease characterized by loss of function and death of nerve cells in several areas of the brain leading to loss of cognitive function such as memory and language. "CPXM2 is a protein-coding gene that has been reported to be associated with several human disorders such as developmental diseases, Alzheimer’s disease and schizophrenia, and to promote tumour aggressiveness when active." (PMID 37941029, 2023). "Previous studies have associated the CPXM2 gene to Alzheimer disease, Parkinson’s disease, and schizophrenia." (PMID 30217166, 2018). "Carboxypeptidase X, M14 family member 2 (CPXM2) have been reported to be involved in cell-cell interactions and associated with developmental diseases, late-onset Alzheimer’s disease, and cognitive decline in schizophrenia." (PMID 31651348, 2019).
Hypertension (3 papers, 2022 to 2023). The presence of chronic increased pressure in the systemic arterial system. "Recently, a novel candidate gene encoding the carboxypeptidase X member 2 (CPXM2) was found to be associated with hypertension-induced LVH." (PMID 35216380, 2022). "Cpxm2 deficiency in mice with sustained hypertension results in profound protection against cardiac damage and failure." (PMID 34916661, 2022). "Recently, the gene encoding CPXM2 was found to be associated with the development of hypertension-induced left ventricular hypertrophy (LVH) in mice." (PMID 35216380, 2022). "In this study, we first performed comparative transcriptome analysis of LV tissues of rat models of hypertension, which mapped a novel candidate, i.e., Cpxm2, to a previously identified QTL for LV mass." (PMID 34916661, 2022). "The similar (in vivo) upregulation of Cpxm2 in the hearts of young animals at 4 weeks of age and before the development of sustained hypertension and in (in vitro) isolated cardiomyocytes and cardiofibroblasts corroborated a potential intrinsic role of Cpxm2 in LV remodeling in hypertension." (PMID 34916661, 2022). "Our data support a functional role of CPXM2 as a novel candidate for LVH and adverse cardiac remodeling in hypertension." (PMID 34916661, 2022). "Only Cpxm2 was confirmed in validation experiments because it demonstrated consistent and significant differential expression between the SHRSP and SHSRP-1F344 strains in separate qPCR expression analysis of LV tissue in adult and young rats at 4 and 8 weeks of age without established hypertension." (PMID 34916661, 2022).
cardiac failure (2 papers, 2022 to 2025). "These biological processes are linked to cardiac function, cardiac remodeling and cardiac failure, and their associations thereby substantiate a putative role of CPXM2 in cardiac failure." (PMID 34916661, 2022). "Our subsequent studies in Cpxm2-deficient mice demonstrated a significant impact on maladaptive remodeling and heart failure development in DOCA-salt hypertension." (PMID 34916661, 2022). "The genetic screening of the donor who had colon cancer, prostate cancer, and succumbed to heart failure identified three genes linked to the latter - ARMT1, CPXM2, and SERPINB2 - along with a plethora of genes associated with cancer, including those of colorectal and prostate." (PMID 41234971, 2025).
hepatocellular carcinoma (2 papers, 2021 to 2022). A malignant tumor that arises from hepatocytes. "Several studies demonstrated that CPXM2, FGF2 and NOVA1 might be available biomarkers for cancers such as hepatocellular carcinoma (HCC), ovarian cancer (OC) and non-small cell lung cancer." (PMID 34559577, 2021).
multiple sclerosis (2 papers, 2022 to 2024). A progressive autoimmune disorder affecting the central nervous system resulting in demyelination. "For example, an exome sequencing and genotyping study of over 400 multiple sclerosis patients found a CPXM2 intronic polymorphism significantly associated with aggressive multiple sclerosis." (PMID 39050735, 2024).
mental disorder (1 paper, 2019). A disease that has its basis in the disruption of mental process. "Most studies have related CPXM2 to developmental diseases, mental disorders, and neurodegenerative diseases." (PMID 31651348, 2019).
Obesity (1 paper, 2020). Accumulation of substantial excess body fat. "Obesity group showed a higher mutation frequency of LDHAL6B, CPXM2, HAPLN3, and so on." (PMID 33197880, 2020).
pilocytic astrocytoma (1 paper, 2024). Pilocytic astrocytoma is a rare subtype of low-grade glioma of the central nervous system characterized by a well circumscribed, often cystic, brain tumor with a discrete mural nodule and long, hair-like projections that extend from the neoplastic astrocytes. "Moreover, the anti-human CPXM2 antibody was also tested in three paired samples of CSF EVD and biopsy tissue obtained from patients with pilocytic astrocytoma." (PMID 38539556, 2024).
small cell lung carcinoma (1 paper, 2025). Small cell lung cancer (SCLC) is a highly aggressive malignant neoplasm, accounting for 10-15% of lung cancer cases, characterized byrapid growth, and early metastasis. "For small cell lung cancer, ACADSB, CEACAM6, COX6B1, CPXM2 and IL12RB2 continued to show significant associations." (PMID 41340014, 2025). "Our study identified five candidate proteins for small cell lung cancer: ACADSB, CEACAM6, COX6B1, CPXM2 and IL12RB2." (PMID 41340014, 2025).
tumor (7 papers, 2019 to 2026). "CPXM2 belongs to the M14 family and has been reported to be implicated in a poor prognosis and the promotion of tumor aggressiveness in various malignancies." (PMID 38808557, 2024). "The ROC curve analysis indicated that CPXM2 has good diagnostic value as a biomarker for PA, not only in distinguishing the PA condition from nontumoral controls (CH), with AUC = 0.91, but also from another kind of tumor (MB), with AUC = 0.85." (PMID 38539556, 2024). "Correlation analysis of clinicopathological parameters indicated that the proportion of FAP+ cells correlated with AJCC stage and tumor invasion depth; CPXM2+ cells correlated with tumor location; Epithelial CPXM2+ cells were associated with the patient's age." (PMID 42052481, 2026). "As shown in the screenshot of methylation heterogeneity at CPXM2, an overlapping DHRs was constantly found at the promoter for comparisons between adjacent normal, and normal samples and between tumour and normal samples." (PMID 37941029, 2023). "The highly methylated level between tumor and normal tissues were ALDH1A3, EFEMP1, SPARCL1, CPXM2 and EFEMP1." (PMID 37563710, 2023). "However, whether CPXM2 is involved in oncogenesis or tumor progression remains unclear." (PMID 31651348, 2019). "The cells that showed CPXM2 overexpression in noncancerous bone tissue were osteoblasts, and the tumor cells with CPXM2 expression derived from osteoblasts in tumor tissues." (PMID 31651348, 2019).
cancer (5 papers, 2019 to 2025). A tumor composed of atypical neoplastic, often pleomorphic cells that invade other tissues. "The remaining signature genes, CPXM2, ENPP5, SAMD13, SLC52A1, ZNF682, ZNF835, ZNF571-AS1 and U91328.1, have not been related to carcinoma, yet." (PMID 33672117, 2021).
heart diseases (1 paper, 2022). "Notwithstanding these limitations, it is important to confirm the expression of Cpxm2 in the human heart and to provide preliminary support for the differential regulation of CPXM2 in human heart diseases, which would provide a rationale for further clinical studies." (PMID 34916661, 2022).
CPXM2 also shares sentences with these, for which no sentence is quoted: schizophrenia (3 papers); Parkinson disease (2); adenocarcinoma (1); Apert syndrome (1); cognitive decline (1); colon cancer (1); congenital hydrocephalus (1); experimental autoimmune encephalomyelitis (1); fetal growth restriction (1); late-onset Alzheimers disease (1); lung adenocarcinoma (1); lung carcinoma (1); medulloblastoma (1); neurodegenerative disease (1); non-small cell lung carcinoma (1); ovarian carcinoma (1); preeclampsia (1); prostate carcinoma (1); ROHHAD syndrome (1); small cell carcinoma (1); squamous cell carcinoma (1).